MTOR (mechanistic target of rapamycin kinase)
Diseases named in the same sentence as MTOR in open-access papers (continued):
Sharing a sentence is not in itself a finding about the gene and the disease.
bladder cancer (continued). "By modifying the AKT/mTOR signaling pathway through microRNA regulation, resveratrol promotes autophagy in bladder cancer cells." (PMID 40717210, 2025). "By targeting the PI3K/AKT/mTOR pathway, paclitaxel and curcumin reduce autophagy in the bladder cancer cells." (PMID 40717210, 2025). "In bladder cancer models, the mTOR inhibitor Everolimus combined with radiotherapy exhibits significant radiosensitizing effects." (PMID 40725100, 2025). "One of the critical pathways implicated in bladder cancer progression and resistance mechanisms is the phosphoinositide 3-kinase (PI3K)/AKT/mammalian target of rapamycin (mTOR) signaling pathway." (PMID 40604062, 2025). "In vitro studies revealed that Everolimus (RAD001) markedly reduces the clonogenic survival of bladder cancer cells and enhances radiotherapy efficacy by inhibiting downstream mTOR signaling, such as p-S6 phosphorylation, and regulating the cell cycle." (PMID 40725100, 2025). "Considering the complexity of the mTOR signaling pathway, further studies focusing on the different members of the mTOR complex and other proteins involved in the pathway are needed to identify specific targets of amiodarone in bladder cancer." (PMID 40353763, 2025). "For instance, EIF3G modulates the mTOR signaling pathway, inhibiting the proliferation and metastasis of bladder cancer cells." (PMID 41277807, 2025). "The PI3K/AKT/mTOR pathway, which consists of phosphatidylinositol 3‐kinase and protein kinase B, is constitutively activated in almost 40% of bladder cancers." (PMID 41179371, 2025). "In conclusion, in addition to the effects of amiodarone on AKT, the drug consistently reduced p-mTOR and p-S6 in the four bladder cancer cell lines, suggesting that the anticancer effect of amiodarone in bladder cancer is mediated by the inhibition of mTOR." (PMID 40353763, 2025). "The PI3K/AKT/mTOR pathway represents one of the most frequently activated signaling networks in bladder cancer, with alterations observed in approximately 50% of cases." (PMID 41438986, 2025). "In one preclinical study, TAMs increased the resistance of bladder cancer cells to cisplatin by activating the β-catenin/mTOR/CDK6 signaling pathway, which promoted their transition to M2-like macrophages." (PMID 39757995, 2025). "In conclusion, drugs related to ferroptosis and mTOR have provided hope in the treatment of bladder cancer." (PMID 38583115, 2024). "Knockdown of hsa_circ_0000520 significantly inhibited PTEN protein levels and increased the phosphorylation levels of PI3K, AKT, and mTOR in bladder cancer cells." (PMID 39237880, 2024). "The underlying mechanism involves RAC3's regulation of the PI3K/AKT/mTOR pathway to modulate autophagy, influencing the biological activity of bladder cancer cells." (PMID 38217031, 2024). "The mTOR/STAT3 double knock-down diminished cell viability in two distinct bladder cancer cell lines at half the concentration of each siRNA compared to single targeting of each gene." (PMID 38886756, 2024). "Compared with the control group, the phosphorylation levels of PI3K, AKT, and mTOR were significantly reduced after HSPB6 overexpression, suggesting that HSPB6 inhibited the activation of PI3K/AKT/mTOR signaling pathway in bladder cancer." (PMID 39608715, 2024). "The patient survival data analysis results predicted mTOR and STAT3 as the most associated with bladder cancer." (PMID 38886756, 2024). "The lncRNA ADAMTS9-AS1 stimulates PI3K/Akt/mTOR axis to suppress apoptosis and autophagy in bladder cancer." (PMID 39512820, 2024). "LncUCA1 activates mTOR, by inducing signal transducer and activator of transcription 3 protein, and inhibiting miR-143, thereby upregulating hexokinase 2 and glycolysis in bladder cancer." (PMID 38544804, 2024). "Jolkinolide B enhances the antitumor efficacy of mTOR inhibitors (temsirolimus, rapamycin, or everolimus) against both PTEN-deficient and cisplatin-resistant bladder cancer cells by suppressing AKT signaling and autophagy." (PMID 39497143, 2024).
bladder cancer (continued). "For example, Leu can regulate its own metabolism in HCC, increase glucose availability to tumor cells, or activate the mTOR signaling pathway in pancreatic, breast, and bladder cancers." (PMID 39595578, 2024). "Taken together, ISO suppresses the PI3K/AKT/mTOR pathway in bladder cancer cells and by extension, targets cancer cell metabolism, survival, and growth." (PMID 38339062, 2024). "Considering that MB-10 induced significant anti-bladder cancer cell activity, we tested its potential effect on Akt-mTOR cascade activation." (PMID 38467612, 2024). "Bupivacaine has been reported to induce ferroptosis by inhibiting the PI3K/AKT pathway, accompanied by decreasing mTOR phosphorylation in bladder cancer cells." (PMID 38583115, 2024). "The nexus between mTOR and STAT3, and their association with adverse outcomes in patients with bladder cancer exhibiting elevated expression of both, is corroborated through comprehensive molecular analyses." (PMID 38886756, 2024). "Activation of Akt-mTOR cascade is vital for the growth of bladder cancer and it is an established therapeutic target." (PMID 38467612, 2024). "In recent years, it has been found that type III ferroptosis inducer FIN56 and mTOR inhibitor-Torin2 can induce autophagic ferroptosis by decreasing GPX4 and inhibiting mTOR leading to decreased phosphorylation of ULK1 in bladder cancer." (PMID 38583115, 2024). "Activates mTOR, inducing signal transducer and activator of transcription 3 protein, and inhibiting miR-143, thereby upregulating hexokinase 2 and glycolysis in bladder cancer." (PMID 38544804, 2024). "Research has shown that metformin inhibits bladder cancer development by targeting the PI3k-Akt–mTOR signaling pathway." (PMID 39737155, 2024). "In human bladder cancer cells, treatment with OA subdued proliferation and induced apoptosis through the Akt/mTOR/s6K and ERK1/2 pathways, which are critical for cell growth, signaling, and survival." (PMID 39728433, 2024). "For instance, GPX4 degradation and mTOR inhibition mediated by autophagy play a synergistic role in killing bladder cancer cells." (PMID 38526702, 2024). "In the present study, we showed that TIMM44 is important for Akt-mTOR activation in bladder cancer cells." (PMID 38467612, 2024). "PTEN acts as a key tumor suppressor in bladder cancer via inhibition of the PI3K/AKT/mTOR signaling pathway." (PMID 37497216, 2023). "It is known that the activated PI3K/Akt/mTOR pathway triggers bladder cancer cell migration and invasion." (PMID 37932474, 2023). "In muscle-invasive cancer urothelial cells, hAM homogenate downregulated the PI3K/Akt/mTOR signalling pathway, the key cascade involved in promoting bladder cancer." (PMID 37932474, 2023). "The molecular mechanisms involved in bladder cancer mainly involve EIF3G-related translational activation as well as mTOR signaling pathway activation." (PMID 36755568, 2023). "The UPII-mutant Ha-ras bladder cancer model used here has high mTOR activity, driving tumor growth and progression." (PMID 37370698, 2023). "Isolated from the soft coral Cladiella kashmani, flaccidoxide-13-acetate inhibited the cell migration and invasion of T24 and RT4 bladder cancer cells (1–10 μM), which were associated with a reduction in p-PI3K, p-AKT, and p-mTOR proteins (2.5–10 μM)." (PMID 38132936, 2023). "Dietary kawain also significantly reduces in vivo bladder cancer cell proliferation and stimulates apoptosis, which is coupled with reduced mTOR signaling and altered cancer metabolisms." (PMID 36838656, 2023). "MIR4435-2HG promotes bladder cancer progression, mediates cell cycle (de)regulation and modulates mTOR signaling." (PMID 37355516, 2023).
bladder cancer (continued). "In conclusion, this study proposes a novel METTL3/YTHDF1–RPN2–PI3K/AKT/mTOR regulatory axis that affects bladder cancer cell proliferation and cisplatin sensitivity." (PMID 37108067, 2023). "This study focused on the effect of hAM preparations on the FAK/PI3K/Akt/mTOR signalling cascade in bladder cancer and normal urothelial cells in vitro." (PMID 37932474, 2023). "Frequent driver mutations in bladder cancer, including receptor tyrosine kinases, Ras, PTEN, and PI3K, all pathologically activate PI3K/mTOR signaling." (PMID 37370698, 2023). "By promoting the PI3K/AKT/mTOR signaling pathway, this stimulation facilitates the advancement of bladder cancer." (PMID 37998733, 2023). "And BCG’s further activation of the mTOR pathway appears contradictory towards the treatment of bladder cancer." (PMID 36662841, 2023). "It has been reported that PEGylated recombinant human arginase 1 (BCT-100) induces autophagy and apoptosis by regulating the ROS/AKT/mTOR pathway in bladder cancer cells." (PMID 36593951, 2023). "Our study proposes a novel METTL3/YTHDF1-RPN2-PI3K/AKT/mTOR regulatory axis in bladder cancer cells." (PMID 37108067, 2023). "In the same way, a close correlation between cell-intrinsic PD-L1 signals and the activation of mTOR in bladder cancer cells, promoting cell growth and metastatic cancer spread, has been demonstrated." (PMID 37834467, 2023). "For example, in bladder cancer, miR‐155 in TNTs was transported from highly aggressive to less aggressive cells and activated bladder cancer cell reprogramming via mTOR signaling." (PMID 35832030, 2023). "Molecularly, the UPII-mutant Ha-ras transgenic model mirrors high mTOR activity, which presents in approximately 70% of human urinary bladder cancer." (PMID 36838656, 2023). "Sodium butyrate induced AMPK/mTOR pathway-dependent autophagy via the miR-139-5p/Bmi-1 axis in human bladder cancer cells." (PMID 35897796, 2022). "From these results, we infer that UCHL5 regulates the proliferation and migration of bladder cancer cells through the AKT/mTOR signaling pathway." (PMID 36428630, 2022). "Given that gypenosides are likely to affect the PI3K/AKT/mTOR pathway in bladder cancer cells, which is crucial for cell survival, we evaluated the potential cytotoxic effect of gypenosides in human bladder cancer cell lines." (PMID 35402614, 2022). "Western blotting showed that PI3K/AKT/mTOR signaling was significantly decreased after FXR overexpression in T24 human bladder cancer cells." (PMID 36139556, 2022). "In bladder cancer, there was a significant reduction in cell proliferation between G0 and G1, a decrease in the activation of the Akt-mTOR pathway, and inhibition of cell growth." (PMID 36449944, 2022). "Temsirolimus, an inhibitor of mTOR, was previously found to benefit patients with bladder cancer who were resistant to platinum-based chemotherapy." (PMID 35402614, 2022). "In bladder cancer, abnormal protein glycosylation was also investigated as associated with PI3K/Akt/mTOR pathways." (PMID 36229592, 2022). "It sensitizes human cholangiocarcinoma to cisplatin and counteracts resistance to the mTOR inhibitor everolimus in bladder cancer cells." (PMID 36230603, 2022). "ThePIK3/AKT/mTOR signaling pathway plays a critical role in the development and prognosis of bladder cancer." (PMID 36408130, 2022). "This compound also activates the autophagy pathway in bladder cancer cells by modulated the Akt/mTOR signaling pathway through the regulation of microRNA expression." (PMID 36428613, 2022). "Mechanistically, gypenosides induced the apoptosis of bladder cancer cells via inactivation of the PI3K/AKT/mTOR signaling pathway." (PMID 35402614, 2022). "As expected, gypenosides displayed apoptosis-inducing properties in bladder cancer cells by inactivating the PI3K/AKT/mTOR signaling pathway in vitro." (PMID 35402614, 2022).
bladder cancer (continued). "Jolkinolide B (JB) inhibited both AKT signaling and cytoprotective autophagy, potentiating the anti-proliferative efficacy of the mTOR inhibitor in both PTEN-deficient and cisplatin-resistant bladder cancer cells." (PMID 36076996, 2022). "According to RNA-Seq analyses and Western blotting experiments, the expression of c-Myc, SLC25A19, and ICAM5 was modified as a result of UCHL5 activating AKT/mTOR signaling in bladder cancer cells." (PMID 36428630, 2022). "mTOR signalling is known to be affected in most cancers and alteration of this pathway occurs in about 72% of bladder cancers." (PMID 35035776, 2022). "Here, we report that the deubiquitinating enzyme, ovarian tumor domain-containing protein 5 (OTUD5), can activate the mTOR signaling pathway, promote cancer progression, and show its oncogenic potential in bladder cancer." (PMID 36085200, 2022). "This newly defined UCHL5-AKT/mTOR-c-Myc axis represents a new therapeutic target for the treatment of bladder cancer." (PMID 36428630, 2022). "Combined, we suggest that the RAC3 inhibition induces autophagy to impair the migration of bladder cancer cells via the PI3K/AKT/mTOR pathway." (PMID 35847878, 2022). "Aberrant activation of the Akt/mTOR pathway is closely related to pro-survival and drug resistance properties in bladder cancer." (PMID 36230603, 2022). "Data identified that in the low HER2 cohort and different ATM levels (high/low); ABL1, SMAD4, RB1 and PARP1 were significantly upregulated and AKT1, AKT2, TSC2, RPTOR and mTOR were significantly downregulated in bladder cancer." (PMID 36056635, 2022). "The inhibition of cytoprotective autophagy by JB enhanced the sensitivity of bladder cancer cells to mTOR inhibitors such as temsirolimus, rapamycin, and everolimus." (PMID 36076996, 2022). "This is notable, since genetic alterations within the PI3K/Akt/mTOR pathway have been noted in 42% of bladder cancer cases." (PMID 36232303, 2022). "RNA-seq results and immunoblotting experiments confirmed that STIL enhanced the PI3K/AKT/mTOR pathway, resulting in increased c-myc expression which ultimately promoted the occurrence and progression of bladder cancer." (PMID 36497260, 2022). "Bladder cancer shows high levels of mTOR activity in approximately 70% of urothelial carcinomas, suggesting a key role for this pathway in this cancer." (PMID 35326708, 2022). "Our observation is consistent with previous reports by Sathe and colleagues, who indicated that only simultaneous inhibition of PI3K and mTOR inhibits bladder cancer cell proliferation." (PMID 36276073, 2022). "Targeting the phosphatidylinositol-3 kinase/protein kinase B/mammalian target of rapamycin (PI3K/Akt/mTOR) signalling pathway is a promising strategy for the treatment of various cancers, including bladder cancer (BC)." (PMID 35783514, 2022). "More specifically, progranulin also protects bladder cancer cells from cisplatin, and promotes proliferation of bladder cancer cells and hepatocellular carcinoma cells via Akt, mTOR, and ERK protein." (PMID 33490663, 2021). "Our previous studies have reported the preferential targeting of the PI3K/Akt/mTOR pathway by the AZ+SFN combination on several bladder cancer pro-survival mechanisms." (PMID 34316328, 2021). "Zhai and Xu found that the suppression of miR-126 mediated by the overexpressed lnc-ATB increases KRAS mRNA and protein, consequently activating PI3K/AKT and mTOR pathways in bladder cancer." (PMID 33498521, 2021). "In fact, MTOR protein is a key downstream protein kinase in the PI3K/AKT signaling pathway, with mutations occurring in approximately 40% of bladder cancer cases." (PMID 33407469, 2021). "Plumbagin, a natural plant-derived drug extracted from Chinese herbals, promotes apoptosis and stops the migration of bladder cancer cells in vitro and in vivo by ROS generation and inhibition of Akt/mTOR." (PMID 34073079, 2021).
bladder cancer (continued). "The mTOR signaling pathway is one of the most investigated therapeutic targets in bladder cancer research." (PMID 34349798, 2021). "Recent investigations indicate that mTOR/ROS is not only involved in autophagy and apoptosis regulation but also controlling bladder cancer cell migration in vitro and in vivo." (PMID 34073079, 2021). "The constitutive activation of the phosphatidylinositol 3-kinase/protein kinase B/mechanistic target of rapamycin (PI3K/Akt/mTOR) pathway has been documented in more than 40% of bladder cancers." (PMID 34073079, 2021). "The AKT/mTOR pathway is critical for bladder cancer (BC) pathogenesis and is hyper-activated during BC progression." (PMID 32007952, 2020). "Several microRNAs (miRNAs) have been reported to interact with the PI3K/Akt/mTOR signaling pathway with a different possible role in proliferation and apoptosis in bladder cancer." (PMID 33292283, 2020). "The investigators suggested that curcumin in EJ bladder cancer cells prevents the activation of PI3K thus suppresses the downstream activation of mTOR and constitutive activation of proto-oncogenes such as the c-MYC." (PMID 33292283, 2020). "ATG5 and ATG7 knockout mouse models would also help to understand the possible role of SCFA on autophagy, as for example, butyrate induced mTOR pathway-activated autophagy in bladder cancer cells and nasopharyngeal carcinoma cells." (PMID 32664466, 2020). "To compare the efficacy of these drugs in bladder cancer cells differing in their mutation status, we studied 253J-BV (PI3KCA-mutated and mTOR wild-type) cells under the same setting." (PMID 32325639, 2020). "Targeting the PI3K/AKT/mTOR pathway with small-molecule inhibitors is an emerging field in bladder cancer." (PMID 33240083, 2020). "Combined Hsp90/mTOR (mammalian target of rapamycin) inhibition is a promising therapeutic approach for TSC1-mutant bladder cancer." (PMID 32842545, 2020). "Here, we found that blockage of O-GlcNAc induces cell autophagy in bladder cancer cells through an mTOR-independent pathway." (PMID 32174982, 2020). "The phosphoinositide 3 kinase (PI3K)/protein kinase B (AKT)/mammalian target of rapamycin (mTOR) pathway is the key driver of carcinogenesis and progression in bladder cancer." (PMID 32325639, 2020). "As pointed out in the previous section, PI3K/AKT/mTOR pathway plays an important role in bladder tumorigenesis, conferring PI3K/AKT/mTOR potential targets in bladder cancer." (PMID 33585182, 2020). "Of these, an inhibitor of the mTOR molecular pathway was further investigated and found to significantly delay the growth of many bladder cancer cell lines." (PMID 33255925, 2020). "Our data demonstrated that all of the CWS-loaded formulations, including CWS, inhibited the growth of bladder cancer cells through mTOR inhibition and AMPK activation, accompanied by ROS accumulation and prolonged ER stress, to induce apoptosis." (PMID 33302414, 2020). "A recent investigation shows that the influence of SFN on mTOR-Akt signaling in bladder cancer leads to a significant increase in Akt phosphorylation (pAkt) in tumor cells following chronic everolimus administration." (PMID 32759798, 2020). "In conclusion, we demonstrate the synergistic effect of the combination therapy with AKT (AZD5363) and mTOR (AZD2014 and BEZ235) inhibitors against bladder cancer cells with PI3KCA and mTOR mutations." (PMID 32325639, 2020). "The anti-tumor properties of these compounds in bladder cancer are well-studied but data regarding its influence on mTOR signaling modulating miRNAs require further investigations to better understand its mechanism of action." (PMID 33292283, 2020). "One way of tackling bladder cancer is to inhibit mTOR, where anomalous interconnected signaling pathways converge." (PMID 32759798, 2020). "More than 40% of bladder cancers exhibit constitutive activation of the phosphatidylinositol 3-kinase/protein kinase B/mechanistic target of rapamycin (PI3K/AKT/mTOR) pathway." (PMID 32466578, 2020).